IGFBP3 (insulin like growth factor binding protein 3)
Diseases named in the same sentence as IGFBP3 in open-access papers (continued):
Sharing a sentence is not in itself a finding about the gene and the disease.
bladder cancer (13 papers, 2005 to 2025). "Plasma levels of IGF-1 and IGF binding protein-3 (IGFBP-3) have been shown to be an association with bladder cancer risk." (PMID 28348577, 2017). "Moreover, a lower preoperative plasma IGFBP-3 level was associated with metastases to regional lymph nodes, bladder cancer progression, and survival." (PMID 23437204, 2013). "Overexpressed GSDMB promoted cancer cell growth via interacting with STAT3 to elevate the phosphorylation level of STAT3, which increased the expression of HK2, LDNA, ENO2, and IGFBP3 to enhance the glycolysis of bladder cancer cells." (PMID 34326684, 2021). "Urine from 157 bladder cancer patients and controls was collected prospectively and IGFBP-3 levels were measured by ELISA." (PMID 16052224, 2005). "Additionally, this study illustrates that SFN-enhanced insulin-like growth factor-binding protein-3 (IGFBP-3) also plays a role in inducing apoptosis in bladder carcinoma." (PMID 34638282, 2021). "In conclusion, GSDMB regulates IGFBP3 expression through the STAT3 pathway in bladder cancer." (PMID 34326684, 2021). "Emerging evidence indicates that IGF-I and IGFBP-3 may also play a role in the development of bladder cancer." (PMID 23437204, 2013). "However, insulin-like growth factor binding protein 3 mRNA was the most strongly differentially expressed gene in both arrays and this confirmed its upregulation in urine of bladder cancer patients (n=157, P<0.01)." (PMID 16052224, 2005). "Furthermore, we found that STAT3 could bind to the promoter of IGFBP3, indicating that STAT3 acted as a transcription factor to initiate the transcription of IGFBP3 in bladder cancer cells." (PMID 34326684, 2021). "As insulin-like growth factor binding protein 3 (IGFBP-3) was one of the most induced and expressed genes in cancer and normal urothelia in vitro and on the in vivo array, in a separate set of 157 urine samples from bladder cancer patients and controls we analysed protein levels of IGFBP-3." (PMID 16052224, 2005). "STAT3 has been shown to affect cellular metabolism, through increased glucose consumption, and lactate production in bladder cancer, through increased transcription of LDHA, ENO2, HK2, and IGFBP3." (PMID 36230984, 2022). "In a US case-control study, patients with bladder cancer have higher plasma levels of IGF-1 and lower levels of IGFBP-3 than controls." (PMID 23437204, 2013). "The finding of raised IGFBP-3 in the urine of bladder cancer patients has not been previously noted." (PMID 16052224, 2005).
esophageal cancer (13 papers, 2012 to 2025). A primary or metastatic malignant neoplasm involving the esophagus. "The low IGFBP-3 level is a promising predictor for high-risk, poor prognosis, and unfavorable tumor stage and metastasis of esophageal cancer." (PMID 27978831, 2016). "Herein, we conducted a meta-analysis to comprehensively evaluate the association between the low IGFBP-3 level and the risk, overall survival and clinical pathological characteristics of esophageal cancer." (PMID 27978831, 2016). "Our study revealed that the IGFBP-3 was another potential diagnostic and prognostic biomarker for esophageal cancer." (PMID 27978831, 2016). "Our meta-analysis suggests that for esophageal cancer, the low IGFBP-3 level is associated with high cancer risk, poor prognosis, and unfavorable tumor stage and metastasis." (PMID 27978831, 2016). "The present study is the first meta-analysis to assess the association between the low IGFBP-3 level and the risk, overall survival, and clinical pathological characteristics of esophageal cancer." (PMID 27978831, 2016). "There were four eligible studies for the analysis of the correlation between the low IGFBP-3 level and the risk of esophageal cancer." (PMID 27978831, 2016). "In order to comprehensively assess the correlation between low IGFBP-3 level and the risk, overall survival and clinical pathological characteristics of esophageal cancer, we conducted the current meta-analysis incorporating seven eligible studies." (PMID 27978831, 2016). "Herein, we aimed to comprehensively assess the association between the low IGFBP-3 level and the risk, overall survival and clinical pathological characteristics of esophageal cancer." (PMID 27978831, 2016). "Our results show that for the risk of cancer, individuals with low IGFBP-3 level are more likely to suffer from esophageal cancer." (PMID 27978831, 2016). "Similar result was reported that low serum IGFBP3 level may be related to poor prognosis of esophageal cancer, increased cancer risk and tumor metastasis." (PMID 36409444, 2022). "As for esophageal cancer, a previous study, aimed to explore the clinical and prognostic significance of IGFBP-3 in patients with esophageal cancer, suggested that both the clinical pathological classifications and poor overall survival were associated with the low IGFBP-3 level." (PMID 27978831, 2016). "There is a controversy that whether the IGFBP-3 level is associated with the clinical pathological characteristics and overall survival of esophageal cancer patients." (PMID 27978831, 2016). "Recently, Pur-α was shown to promote esophageal cancer progression by forming SGs and suppressing translation initiation of IGFBP3." (PMID 37443145, 2023). "We presented heatmap and prognostic value of DNA methylation clustering the expression levels of the IGFBP3 gene in esophageal carcinoma (ESCA) and stomach adenocarcinoma (STAD)." (PMID 36409444, 2022). "IGFBP3 mediates the induction of CD44-high cells by suppressing reactive oxygen species (ROS) in the esophageal cancer microenvironment." (PMID 34404882, 2021). "In oesophageal cancer, IGFBP-3 was reported to inhibit tumour cell growth and induce apoptosis after radiotherapy." (PMID 32093285, 2020). "Our study also revealed that the IGFBP-3 level in patients with esophageal cancer was significantly lower than that in healthy participants." (PMID 27978831, 2016). "For survival status, the OR was 4.490 (95% CI: 2.207–9.093, p = 0.000), signifying that the low IGFBP-3 level was correlated with the survival status of patients, and esophageal cancer patients with low IGFBP-3 level occupied a lower survival rate." (PMID 27978831, 2016). "As for the overall survival, the esophageal cancer patients in low IGFBP-3 level have lower 3-year survival rate than those in relatively high IGFBP-3 level." (PMID 27978831, 2016).
esophageal cancer (continued). "For the risk of esophageal cancer, the OR was 2.342 (p = 0.000), indicating that individuals with lower IGFBP-3 level were more likely to suffer from esophageal cancer, compared to those with relatively high IGFBP-3 level." (PMID 27978831, 2016). "In esophageal cancer, the accumulation of inflammation-derived secretory factors, including IL-6, Insulin-like growth factor-binding protein-3 (IGFBP-3), and CXC motif chemokine ligand 16 (CXCL16), results in the upregulation of CD38 in myeloid-derived suppressor cells (MDSCs)." (PMID 40382743, 2025). "Loss of IGFBP3 also mediates acquired resistance to EGFR tyrosine kinase inhibitors, and upregulation of IGFBP3 is reportedly associated with increased chemosensitivity of esophageal cancer cells to nimotuzumab (anti-EGFR monoclonal antibody) with CDDP." (PMID 29849953, 2018). "In addition, IGFBP-3 has also been identified as a gene that is most highly up-regulated in EGFR-overexpressing esophageal cancer cell lines and primary esophageal tumors." (PMID 23232108, 2012). "It was suggested that Smad3-P27/P21-cyclin E1/CDK2-phosphorylated retinoblastoma protein pathways might be involved in IGFBP-3-mediated radiosensitivity transition in esophageal squamous cell carcinoma (ESCC) the most prevalent histologic type of esophageal cancer in China and eastern countries." (PMID 27978831, 2016). "Increased expression of IGF1R, IGFBP3, IGFBP4, IGFBP7, and IGFBP8 was reported in human esophageal cancer, while the expression of IGFBP2 and IGFBP6 was reduced." (PMID 32041673, 2020). "For patients in TNM category, the OR was 4.110 (95% CI: 1.850–9.160, p = 0.000), signifying that for esophageal cancer patients in TNM category, the IGFBP-3 level in patients with III–IV tumor stage was significantly lower than that in patients with other tumor stages." (PMID 27978831, 2016). "Secondly, the cut-off value of IGFBP-3 level for the determination of esophageal cancer was not quite the same, which might result in some bias for our meta-analysis." (PMID 27978831, 2016). "For patients in T category, the OR was 2.870 (95% CI: 1.510–5.450, p = 0.005), implying that for esophageal cancer patients in T category, patients whose tumors extended invasion in other organs had lower IGFBP-3 level than those without invasion in other organs." (PMID 27978831, 2016). "For patients in M category, the OR was 3.270 (95% CI: 1.670–6.400, p = 0.001), suggesting that for esophageal cancer patients in M category, patients whose tumor cells metastasized to distant organs (beyond regional lymph nodes) had lower IGFBP-3 level than those without distant metastases." (PMID 27978831, 2016).
esophageal squamous cell carcinoma (13 papers, 2012 to 2022). Esophageal squamous cell carcinoma (ESCC) is a type of esophageal carcinoma (EC) that can affect any part of the esophagus, but is usually located in the upper or middle third. "Esophageal squamous cell carcinoma cells with IGFBP3 knockdown had enhanced relative radioresistance." (PMID 33712045, 2021). "In agreement with our data, a link between EGFR and IGFBP-3 has also been described for primary human esophageal cells and esophageal squamous cell carcinomas indicating that EGFR indeed directly regulates IGFBP-3." (PMID 29445126, 2018). "In esophageal squamous cell carcinoma, like TNBC, IGFBP-3 is highly expressed and is associated with poor patient survival." (PMID 28778177, 2017). "In esophageal squamous cell carcinoma, IGFBP3 promotes tumor progression in a subset of tumor cells with a concurrent high expression of CD44." (PMID 29108245, 2017). "In esophageal squamous cell carcinoma cells in vitro, IGFBP-3 induces cells expressing high levels of CD44, a transmembrane glycoprotein involved in tumor growth and progression." (PMID 28778177, 2017). "Nimotuzumab also promoted radiosensitivity of esophageal squamous cell carcinoma cells by up-regulating IGFBP-3 through EGFR-dependent pathway." (PMID 25918252, 2015). "It suggested that IGFBP-3 promoted esophageal squamous cell carcinoma (ESCC) cell cycle transition from G0/G1 to S phase via Smad3-P27/P21-cyclin E1/cyclin-dependent kinase (CDK2)–phosphorylated retinoblastoma protein (pRb) pathway signaling." (PMID 26670461, 2015). "Insulin-like growth factor binding protein-3 (IGFBP-3) plays an essential role in radiosensitivity of esophageal squamous cell carcinoma (ESCC)." (PMID 26670461, 2015). "Insulin-like growth factor-binding protein-3 (IGFBP-3) is suggested to predict the radiosensitivity and/or prognosis of patients with esophageal squamous cell carcinoma (ESCC)." (PMID 26370590, 2015). "However, the reduction in IGFBP-3 in response to hypoxia in REC is contrary to work in H9c2 myocardial cells and esophageal squamous cell carcinoma xenografts where IGFBP-3 is increased in response to hypoxia." (PMID 27439004, 2016).
Hypertension (13 papers, 2010 to 2023). The presence of chronic increased pressure in the systemic arterial system. "Research on SNPs of the IGFBP3 rs11977526 gene and hypertension indicated an association of these factors, as found in a study involving East African people, was associated with the risk of such disease." (PMID 34001234, 2021). "In our analysis, the dominant and recessive showed a strong association of TT and AA genotypes of the NOS3 and IGFBP3 genes, respectively, with hypertension." (PMID 34001234, 2021). "The less frequent genotypes of the NOS3, rs1799983, TCF7L2 rs7903146, and IGFBP3 rs11977526, SNPs were associated with a higher prevalence of hypertension in comparison with the ancestral and heterozygous genotypes." (PMID 34001234, 2021). "Brazilian Afro-descendant women with the TT genotype for the NOS3 gene and the AA genotype for the IGFBP3 gene are more susceptible to hypertension." (PMID 34001234, 2021). "This study did not confirm previous cross-sectional studies describing associations of IGFBP-3 and IGF-I with hypertension, but rather revealed a link between IGFBP-3 and lipid concentrations in young males." (PMID 30061864, 2018). "Herein, we evaluated the association of seven SNPs of IGFBP1 and IGFBP3 with hypertension in a community-based case-control study of the Chinese Han population as well as with CCVD in a prospective follow-up study." (PMID 29100429, 2017). "rs2132572 and rs3110697 of IGFBP3 showed significant associations with hypertension in the whole study population." (PMID 29100429, 2017). "In the present study, we first showed that rs2132572 and rs3110697 at IGFBP3 are associated with an increased risk of hypertension." (PMID 29100429, 2017). "In the case-control study, rs2132572 and rs3110697 at IGFBP3 were significantly associated with hypertension, and the odds ratios (ORs) of rs2132572 (CT+TT vs. CC) and rs3110697 (GA+AA vs. GG) were 1.235 (P=0.002) and 1.176 (P=0.013), respectively (PFDR<0.05)." (PMID 29100429, 2017). "A higher IGFBP3 level was associated with hypertension, CHD, ischemic heart disease, and atherosclerosis." (PMID 29100429, 2017). "Three single-nucleotide polymorphisms (SNPs) in IGFBP1 and four SNPs in IGFBP3 were selected for genotyping in 2,012 hypertension cases and 2,210 healthy controls and 4,128 subjects were followed up for a median of 5.01 years." (PMID 29100429, 2017). "rs2132572 and rs3110697 in IGFBP3 presented statistical associations with an increased risk of hypertension." (PMID 29100429, 2017). "In this study, there was a higher predisposition for hypertension in the presence of TT and AA genotypes for the NOS3 and IGFBP3 genes, respectively." (PMID 34001234, 2021). "Future molecular studies are needed to reveal the important roles of eNOS and IGFBP3 when they are related to hypertension." (PMID 34001234, 2021). "In summary, the present study showed that DNA methylation in the promoters of PRDM6, HDAC9, IGFBP3, LRRC10B, SYT7, PDE3A, TBX2 and C17orf82 genes were significantly associated with BP or hypertension." (PMID 35087571, 2021). "In the dominant model of oxidative stress (NOS3: GG + IGFBP3: GG vs NOS3 GT + TT; IGFBP3: AG + AA), women had a prevalence of 34.7% hypertension (PR = 1.42; 95% CI 1.12–1.79; p = 0.003)." (PMID 34001234, 2021). "This study aimed to investigate the prevalence of polymorphisms NOS3; rs1799983, IGFBP3; rs11977526 and TCF7L2; rs7903146 in Brazilian women of African descent and their association with hypertension." (PMID 34001234, 2021). "We found that DNA methylations in the promoters of PRDM6, HDAC9, IGFBP3, SYT7, TBX2 and C17orf82 were significantly associated with BP or hypertension in the Chinese Han population." (PMID 35087571, 2021). "Regarding IGFBP3; rs11977526 SNP, the prevalences of hypertension among women with GG, GA and AA genotypes were 24.1%, 26.4% and 62.0%, respectively, with a statistically significant difference between AA and GG (PR = 1.59; 95% CI 1.27–1.98; p < 0.001)." (PMID 34001234, 2021).
Hypertension (continued). "The baseline characteristics of our study population demonstrated that men were older, more often smokers, more often affected by hypertension and had lower serum IGFBP-3 concentrations than women." (PMID 23237568, 2012). "Therefore, IGFBP3 serum levels are closely related to the production of endothelial NO and, consequently, to oxidative stress and hypertension." (PMID 34001234, 2021). "However, in the recessive model of oxidative stress (NOS3: TT + IGFBP3: AA vs NOS3: GG + GT IGFBP3: GG + AG), they had a prevalence of 77.0% hypertension (PR = 2.07; 95% CI1.78–2.42 p < 0.001)." (PMID 34001234, 2021). "Therefore, IGFBP1 and IGFBP3 are of particular interest as candidate genes for hypertension." (PMID 29100429, 2017). "The SNPs in the NOS3 rs1799983, IGFBP3 rs11977526, and TCF7L2 rs7903146 genes can directly influence the protein expression in the respective genes, making them important biomarkers for the development of hypertension." (PMID 34001234, 2021). "The IGFBP3 levels were not different between the hypertension cases and controls." (PMID 29100429, 2017).